APC (APC regulator of Wnt signaling pathway)
Diseases named in the same sentence as APC in open-access papers (continued):
Sharing a sentence is not in itself a finding about the gene and the disease.
pancreatic cancer (continued). "Moreover, the authors showed that, by targeting APC, miR-205-3p could encourage cell proliferation in pancreatic cancer." (PMID 37628628, 2023). "However, only miR-103 was directly involved in the regulation of pancreatic cancer-associated processes: E-cadherin signalling events (CDH1), TGF beta signalling pathway (TGFBR2, APC, CDH1, CREBBP, EP300, SMAD3, TSC2), and altered TFG-beta SMAD dependent signalling (TGFBR2, SMAD3, and FBXW7)." (PMID 29285254, 2017). "Specific polymorphisms in the APC and CD24 genes may play a role in pancreatic cancer development." (PMID 26394139, 2015). "Pancreatic cancer shows 83% of KRAS and 2% of APC, whereas gallbladder cancer shows frequencies of 10% and 3%, respectively." (PMID 40916582, 2025). "MiR-137-mimic significantly promoted AXIN1 and APC, GSK-3β, the phosphorylation of β-catenin on Ser45 expression, and reduced the β-catenin of cytoplasm and nuclear expression in pancreatic cancer cells." (PMID 30866999, 2019). "We investigated methylation levels at selected CpG sites in the CpG rich regions at the promoter regions of p16, RARbeta, TNFRSF10C, APC, ACIN1, DAPK1, 3OST2, BCL2 and CD44 in the blood of 30 pancreatic tumor patients and in the blood of 49 matching controls." (PMID 22629410, 2012). "Neuroendocrine pancreatic cancer, but not the major population of pancreatic cancer, also exhibits hypermethylation in APC promoter 1A." (PMID 33968756, 2021). "It has been shown that pancreatic tumors failed to develop following conditional inactivation of APC in the pancreas, suggesting that APC is required for tumorigenesis in the pancreas." (PMID 26394139, 2015). "APC is not mutated and β-catenin is not upregulated in MIA-Paca2 cells, a representative cell line of pancreatic cancer." (PMID 24348824, 2014). "Moreover, RARbeta in blood correlated with TNFRSF10C, CD44, ACIN1, APC, p16 and LINE-1 in pancreatic tumor tissue." (PMID 22629410, 2012).
ovarian carcinoma (52 papers, 2000 to 2025). A malignant neoplasm originating from the surface ovarian epithelium. "Hyperactivity of β-catenin, in the case of ovarian cancer, and mutations of AXIN, CTNNB1, and APC genes were observed in epithelial ovarian cancer (EOC)." (PMID 34439332, 2021). "Mechanism analysis showed FAM83B interacted with APC to inhibit Wnt pathway activity, causing ovarian cancer cisplatin resistance." (PMID 33423038, 2021). "The result of APC mutation is controversial, compared with previous tissue DNA studies; thus further study is needed to clarify the role of APC mutation in ovarian cancer." (PMID 33207545, 2020). "The objective of this study was to evaluate the role of activated protein C (aPC), known to be a physiological anticoagulant, in ovarian cancer cell activation as well as in loss of clotting of cancer ascitic fluid." (PMID 26082331, 2015). "APC mutations contribute significantly to colon carcinogenesis but also have been implied in ovarian cancer development." (PMID 21390237, 2011). "Mutations in the APC gene are associated with colon, colorectal, and ovarian cancers." (PMID 39376879, 2024). "Mutations of adenomatous polyposis coli (APC) or Axin occur rarely in ovarian cancer." (PMID 16479254, 2006). "In our experiment, we noted a decrease in the expression of the APC gene in fibroblasts after treatment with ovarian cancer-derived exosomes." (PMID 36012171, 2022). "The analysis of the APC gene expression, which is one of the elements of the Wnt pathway, showed that exosomes derived from ovarian cancer cells lead to a significant reduction in the expression of this gene in normal fibroblasts." (PMID 36012171, 2022). "In summary, we found FAM83B inhibits ovarian cancer cisplatin resistance through interacting with APC to suppress Wnt pathway activity, and provides a target for ovarian cancer therapy." (PMID 33423038, 2021). "We inhibited APC using small molecule compound in FAM83B overexpression ovarian cancer cells and found cisplatin resistance was increased, suggesting FAM83B inhibited cisplatin resistance through interacting with APC to inhibit Wnt pathway." (PMID 33423038, 2021). "There was statistically significant heterogeneity in APC promoter hypermethylation in ovarian cancer in relation to tumor grade and tumor stage (I2 = 68.5 %, P = 0.013; I2 = 61.0 %, P = 0.025; respectively), using the random-effects model." (PMID 27670526, 2016). "Twelve studies assessed the correlation between APC promoter methylation and ovarian cancer, including 10 cancer-normal studies, 7 cancer-benign studies and 5 cancer-LMP studies." (PMID 27670526, 2016). "APC promoter hypermethylation has been reported in some cancers, including ovarian cancer, which indicates that it can become a noninvasive biomarker for cancer detection." (PMID 27670526, 2016). "There were significant increases of β-catenin and GSK3β, while APC was reduced in ovarian cancer compared to the normal ovary." (PMID 14520463, 2003). "Most of the LPVs detected did not match the tumor diagnosed (e.g., APC variants in individuals with breast and ovarian cancer)." (PMID 38201524, 2023). "The lower decrease in APC gene expression in exosome-treated fibroblasts from drug-treated ovarian cancer cells indicates that these drugs may also contribute to the inhibition of the metastatic process at this stage." (PMID 36012171, 2022). "Mutations in CTNNB1 (β-catenin) are identified in 16%–54% of endometrioid ovarian cancer patients, and other mutations in APC, AXIN1, and AXIN2, which are key downstream proteins of the Wnt/β-catenin pathway, are also found in different types of ovarian cancer." (PMID 36185280, 2022). "Inhibition of APC in FAM83B overexpression ovarian cancer cell increased cisplatin resistance." (PMID 33423038, 2021).
ovarian carcinoma (continued). "Through cooperating with MDM2 (murine double minute 2 gene), APC might be involved in drug resistance in ovarian cancer." (PMID 33968756, 2021). "Methylation of hMLH1, analyzed in 138 plasma samples predicted poor survival (hazard ratio: 1.99) while CDH1, CDH13, and APC (out of a 15 gene panel) analyzed in peritoneal fluid from 57 ovarian cancer patients could predict overall survival." (PMID 31608277, 2019). "However, the correlation between APC promoter hypermethylation and ovarian cancer (OC) remains to be clarified." (PMID 27670526, 2016). "Moreover, we also validated the clinicopathological significance of hypermethylated APC in ovarian cancer." (PMID 27670526, 2016). "The investigated gene promoters were chosen from loci previously reported to be methylated in ovarian cancer (n = 7; APC, CDH13, MGMT, MLH1, p14ARF, p16INK4a, RASSF1A) and from loci methylated in other tumour types (n = 6; ADAMTS1, CRABP1, HOXA9, HOXB5, NR3C1, SCGB3A1)." (PMID 17623056, 2007). "Previous evidence indicates that the RING-domain E3 ubiquitin ligases including Cullin-RING E3 ligase complexes such as SCF complex (SKP1, Cullin and F-box protein), the APC/C complex, as well as monomeric XIAP, MDM2, MUL-1, Pirh2, and SIAH2 may all be associated with ovarian cancer chemoresistance." (PMID 35582023, 2021). "In ovarian cancer, aberrant methylation of CpG islands in tumor suppressor genes, including CDKN2B, BRCA1, APC, RASSF1, and CDH13, is a frequent event compared to that in the normal ovarian surface epithelium." (PMID 31615043, 2019). "Promoter hypermethylation of at least one of six genes (BRCA1, RASSF1A, APC, p14ARF, p16INK4A and DAPK) was observed in 41/50 ovarian cancer serum specimens." (PMID 24821107, 2014). "An overlapping set of seven genes (ABCB1, APC, BRCA1, CDH1, DNAJC15, HIC1 and SULF2) displayed the same methylation changes in the examined set of ovarian carcinoma cell lines." (PMID 20544021, 2010). "APC, CDH13, CRABP1, HOXA9, HOXB5, RASSF1A, and SCGB3A1 were found to be hypermethylated both in the primary tumours and in ovarian cancer cell lines, whereas ADAMTS1 and MGMT were hypermethylated only among cell lines." (PMID 17623056, 2007). "Immortalised human ovarian surface epithelium and ovarian cancer cell cells (OVCAR-3) expressed β-catenin, APC, GSK3β and Lef-1." (PMID 14520463, 2003). "The cisplatin-resistant ovarian cancer cell line A2780-DDP, developed for our investigation, demonstrated a decrease in β-catenin within the cytoplasm but an increase in its phosphorylated form in the nucleus, alongside a reduction in APC." (PMID 38726137, 2024). "Knocking down PYGB also significantly inhibited the expressions of Wnt3a, β-catenin, APC, and Cyclin D1 in ovarian cancer cells, suggesting that, through the Wnt/β catenin signaling pathway, PYGB might regulate the progression of ovarian cancer." (PMID 38334681, 2024). "Besides, high frequency mutation of several pathway components have been observed in ovarian cancer, such as CTNNB1, AXIN1/2, and APC." (PMID 36185280, 2022). "In this study, we found ovarian cancer cells with high FAM38B levels had low cisplatin resistance, mechanism analysis showed FAM83B inhibits cisplatin resistance of ovarian cancer through interacting with APC and inhibiting Wnt pathway." (PMID 33423038, 2021). "In the present study, APC expression was demonstrated in normal ovaries and benign tumours, but was low or absent in malignant ovarian tumours." (PMID 14520463, 2003). "Our result from 5 studies indicated that the correlation between APC promoter hypermethylation and tumor stage was not statistically significant (OR = 0.76, 95 % CI = 0.31–1.88, P = 0.558), including 188 early ovarian cancer patients and 278 advanced ovarian cancer patients." (PMID 27670526, 2016).
colorectal adenocarcinoma (45 papers, 2012 to 2026). The most common type of colorectal carcinoma. "Truncating mutations of RNF43 are more prevalent in MSI tumors and show mutual exclusivity with inactivating APC mutations in colorectal adenocarcinomas." (PMID 40757636, 2025). "Mutations in the APC (adenomatous polyposis coli) gene associated with colorectal adenocarcinoma have been described." (PMID 40725041, 2025). "Patients with colorectal adenocarcinoma, the majority of whom would be expected to harbor APC mutations, showed upregulated CXCL1, 2, and 3 expression at early stages of disease." (PMID 40545113, 2025). "This distinction arises from the frequent presence of loss-of-function APC mutations in colorectal adenocarcinoma, which are strongly associated with long 3′ UTR expression relative to tumors lacking APC mutations." (PMID 39375704, 2024). "Given this, we cannot say with certainty that APC mutations are solely or even primarily responsible for the distinct global patterns of APA that we observed in colorectal adenocarcinoma samples." (PMID 39375704, 2024). "Gardner syndrome is a neoplasic disease that associates intestinal polyposis and colorectal adenocarcinoma with osteomas and soft tissue tumors determined by germline mutations in the APC gene." (PMID 34573902, 2021). "APC mutations have been characterized in adenomatous polyposis and colorectal adenocarcinomas; however, their role in the pathogenesis of neuroendocrine carcinoma remains unclear." (PMID 40491286, 2026). "Colorectal adenocarcinomas are largely driven by mutations in the gene adenomatous polyposis coli (APC), and inherited loss-of-function mutations in APC cause familial adenomatous polyposis, which carries nearly a 100% risk of colorectal adenocarcinoma development at some point in life." (PMID 39375704, 2024). "Molecular profiling of three separate liver nodules, the primary adenocarcinoma of the rectum, and a tumor-free lymph node from patient 1 identified a pathogenic germline mutation in the APC gene and different deleterious somatic mutations in the colorectal adenocarcinoma and the liver nodules." (PMID 37872280, 2024). "In addition, oncogenic truncated APC induced the loss of cholesterol homeostasis in several authentic human colorectal adenocarcinoma cell line models." (PMID 37468468, 2023). "APC mutation is one of the most frequent mutations in colorectal adenocarcinoma." (PMID 37260182, 2023). "Two of eight carrying APC mutations also have KRAS p.G12V/D, which is a general oncogenic feature that was also observed in the five MSS colorectal adenocarcinoma samples also sequenced in our study." (PMID 40757636, 2025). "The frequency of APC alterations in colorectal adenocarcinoma (80.9%) was significantly higher than that in stomach (2.5%), pancreatic (1.7%), and biliary tract (1.7%) adenocarcinomas (p < 0.01)." (PMID 38672586, 2024). "Alterations in the genes involved in the Wnt/β-catenin pathway, mainly APC, were observed in colorectal adenocarcinoma." (PMID 38672586, 2024). "Most studies of APC in colorectal adenocarcinoma focus on the protein’s role in regulating WNT signaling or cytoskeletal organization; however, several studies focused on murine neurogenesis have previously identified APC as an RNA-binding protein." (PMID 39375704, 2024).
colorectal adenocarcinoma (continued). "Comprehensive molecular profiling of GEP-NEC identified APC mutations, particularly in colorectal NEC, with similar frequencies to those in colorectal adenocarcinomas." (PMID 36269546, 2022). "Overall survival was analyzed by selecting Colorectal Adenocarcinoma (TCGA, Nature 2012) and gene APC via cBioPortal for provisional data." (PMID 28515349, 2017). "Lastly, germ-line defects in APC cause FAP, in which affected patients develop hundreds of adenomatous polyps at an early age and ultimately progress to colorectal adenocarcinoma with 100% penetrance." (PMID 28418862, 2017). "Such a hypothesis is concordant with observations from colorectal adenocarcinoma, where homozygous deletions of APC are extremely rare and thought to arise from a need to optimize β-catenin activity." (PMID 39375704, 2024). "Among the adenocarcinomas with APC alterations, 97.1% were colorectal adenocarcinomas." (PMID 38672586, 2024). "Pik3caH1047Rmutations initiate cancers through a non-canonical mechanism: The most common mutation in human colorectal adenocarcinomas results in a truncated APC protein." (PMID 26863299, 2016). "Patients with Turcot’s syndrome typically have a defect in the adenomatous polyposis coli (APC) gene and/or a mutation in DNA mismatch repair (MMR) genes predisposing them to the development of multiple colorectal adenomas, colorectal adenocarcinoma, and primary brain tumors." (PMID 22937526, 2012). "The mutually exclusive alterations in APC and RNF43 has been reported in microsatellite-unstable colorectal adenocarcinomas." (PMID 39011117, 2024). "To that end, we have generated colorectal (adeno) carcinoma-derived epithelial cellular lines (SW480 and HCT116) expressing stably wild-type APC (APC-WT) or the mutant APC-m4 (see STAR Methods)." (PMID 37128612, 2023). "We searched the TCGA database for the presence of altered APC, β-Catenin (CTNNB1) and GSK3β in 526 colorectal adenocarcinoma patient samples (TCGA, PanCancer Atlas)." (PMID 35625868, 2022). "Using TCGA colorectal adenocarcinoma Firehose legacy dataset from cBioPortal platform, we found that the TFRC protein expression was positively correlated with the CTNNB1 protein expression, whereas the CTNNB1 protein expression was negatively correlated with APC mRNA expression." (PMID 36703617, 2023). "Multiple authors reported no Epidermal growth factor receptor, BRAF, KRAS, or Adenomatous polyposis coli (APC) mutations in GCA, suggesting that its molecular pathogenesis is significantly different from that of colorectal adenocarcinoma, although again this was not a unanimous finding." (PMID 35903705, 2022).